SOX2 (SRY-box transcription factor 2)
Diseases named in the same sentence as SOX2 in open-access papers (continued):
Sharing a sentence is not in itself a finding about the gene and the disease.
cancer (continued). "Though it has not yet been tested as an anti-cancer agent, PIP-S2 successfully inhibited SOX2-DNA binding by targeting the SOX2 DNA-binding sequence, thus triggering the differentiation of pluripotent stem cells." (PMID 38612911, 2024). "This non-canonical signaling cascade induces the expression of SRY-Box Transcription Factor 2 (SOX2) and NANOG, promotes the maintenance of cancer stem cell properties and drives metastatic reactivation in the lung, bone, and brain." (PMID 39682261, 2024). "Of the 32 cases that did not progress to cancer within two years, 26 (81%) and 8 (25%) were CK17 and SOX2 positive, respectively." (PMID 39682153, 2024). "Third, cancer stem cells, but not all dormant cancer cells, express stemness markers such as OCT4 and SOX2." (PMID 37760529, 2023). "Furthermore, we show SOX2, one of the most well-known cancer stemness biomarkers, is a downstream target of miR-5047 and that SOX2 mRNA can directly interact with miR-5047 in OS cells, suggesting that WAC-AS1 may regulate the expression of SOX2 via competitively binding with miR-5047." (PMID 37957698, 2023). "Treatment with NOT significantly attenuated cancer stem cells (CSCs)-like phenotypes, namely colony and tumorsphere formation, with the concomitant downregulation of stemness markers OCT4, SOX2, CD133, and upregulated PARP-1 cleavage, dose-dependently." (PMID 37299411, 2023). "As a result, we observed significant enrichment of KDM6B on promoter regions of SOX2 and CD44 but not on SOX9 in detached cancer cells." (PMID 35186918, 2022). "The three ESCC tumors contained an overwhelming majority of cancer cells with notable TP63/SOX2 over-amplification, which was not apparent in EAC cancer cells." (PMID 35785171, 2022). "These THC were characterized by high PD-L1 and stemness markers (SOX2, NANOG, miR-302) as compared with non-fused (CD11b−EPCAM+) cancer cells." (PMID 35053451, 2022). "Thus, behind the scenes of mutual exclusion for SOX2 amplification and YAP1 amplification of these patients in this study, there lies a unique unknown molecular mechanism of ESCC tumorigenesis, distinguished from other cancer types, which needs further investigation." (PMID 35548450, 2021). "We found that cancer cells overexpress epithelial-to-mesenchymal transition markers TWIST1 and SNAI2, as well as stem-like marker CD44 (but not CD133, SOX2 and/or NANOG)." (PMID 33531664, 2021). "We also detected significantly high expression of OCT4, SOX2, KLF4 and BMI1 in the HPV-negative OPC CSCs as compared to the cancer cells, while CD133 expression was not different in the CSCs and the cancer cells." (PMID 34359786, 2021). "The expression of SOX2 and OCT4 was also higher in the breast CSCs, as compared with the non-CSC cancer cells." (PMID 33731668, 2021). "Organoids were also positive for multifunctional stem cell marker and cell-adhesion glycoprotein CD44, however they did not exhibit expression of other cancer stem cell markers such as OCT4, NANOG, SOX2, or ALDH1." (PMID 33732646, 2021). "The effect of the treatment was first evaluated by measuring the expression of stem cell transcription factors SOX2, NANOG, OCT4, SCA-1, and KLF4 for both cell cancer and non-CSC populations." (PMID 29868483, 2018). "We also observed a positive correlation between SOX2 and EGFR expression in stage IV metastatic endometrial carcinoma, but not in early stage cancer." (PMID 30510261, 2018). "Here, we observed that TP63 and SOX2 co-bound to the promoter and super-enhancer regions of CCAT1 and contributed to its transcription activity specifically in SCCs, but not other cancer types." (PMID 30190462, 2018). "While high SOX2 expression promotes lung SCC, adeno-like carcinoma develop largely in the absence of SOX2." (PMID 29596469, 2018).
cancer (continued). "To characterize the CSC-like cells (cells present in the sphere-like aggregates), we compared the expression levels of CD44, OCT-4, SOX2 and SOX9 between CSC-like (spherogenic) and non-CSC (non-spherogenic) UM1 cancer cells with Western blotting." (PMID 24423398, 2013). "Similarly, in a study of head and neck cancer, cancer cells expressed high levels of NANOG, OCT4, SOX2 and EpCAM when ARID1A was absent." (PMID 40429787, 2025). "Additionally, the lack of expression of pluripotency antibodies (Nanog, SOX2, and OCT4) coupled with POU5F1's normal molecular arrangement disputes the cancer stemness paradigm in MEC." (PMID 40478494, 2025). "However, for the purpose of this review, it should be mentioned that is has, so far, not been possible to study anti-cancer drugs targeting AIM2, Sox2 or cGAS-STING pathway exclusively in neutrophils." (PMID 37483598, 2023). "As OCT4, SOX2, Myc, and NANOG transcription factors are essential for normal stem cell propagation, they may also support the existence of cancer stem cells." (PMID 36674511, 2023). "Conversely, the highest macrophage counts in the biopsies of non-smoking/non-drinking patients with OSCC correlated with a lack of cancer stem cells markers, NANOG and SOX2, along with high expression of PD-L1 by these tumors, indirectly pointing to the role of macrophages in immune escape." (PMID 36143308, 2022). "In most cases, SOX2 was negative (11/14 cases) or very focally expressed (about 20% of the cancer cells in 3/14 cases), and ALDH1 was, in most cases (11/14 cases), also expressed in at least 20% of the cancer cells (see color key)." (PMID 35162954, 2022). "Moreover, the increase of the transcriptional expression of Orai3, Nanog and SOX2 in CD133+-A549- and H23 cells when compared to nonsorted cells, demonstrates the increase in the population of cancer stem cells." (PMID 34065942, 2021). "For instance, Sox2 and Bcl-3 cooperate to maintain stemness of embryonal stem cells, STAT3 can convert non-CSCs to CSCs, AKT is involved in maintaining Sox2-dependent cervical CSC activity and CSCs isolated from ERα-positive cancer show a hyperactive PI3K pathway." (PMID 33228022, 2020). "Moreover, the addition of kynurenine to tumorsphere cultivation significantly increased the tumorsphere number of HeLa and SiHa cells, as well as the increased expression of Oct4 or Sox2 but not BMI1, which all belong to the well-known cancer stemness genes." (PMID 32545442, 2020). "Here, we showed that Ezh2 inhibition by DZNEP could reduce Doc-induced gene expression of cancer stem cell markers (Nanog, CD44 and Sox2), supporting the notion that Ezh2 acts on these genes independent of PRC2 complex." (PMID 30621625, 2019). "The expression of previously-reported candidate marker genes, such as CD133, CD44 and ABCG2, which are argued to be related to cancer stem cells, and the transduced genes OCT3/4, SOX2 and KLF4 were not significantly different among the parental A549, OSK-A549-Colony and OSK-A549-SN cells." (PMID 28951614, 2017). "Moreover, actions of EGFR in regulation of cancer stemness markers including OCT4 and SOX2 were not consistent in EOC cells." (PMID 27708225, 2016). "Overall, the significant over-expression of stem cell markers SOX2, OCT4, SOX9 and CD44 suggests that the cells present in spherical aggregates are CSC-like whereas the non-spherogenic, adherent layer of cells are non-CSC cancer cells." (PMID 24423398, 2013). "Unlike the NCCIT cells, expression of OCT4, SOX2 and NANOG could not be detected in any primary cancer cell line tested." (PMID 18847459, 2008). "As numbers of studies found that cell stemness/differentiation may contribute to chemoresistance in cancers, negative correlations between PKM2 expression and stemness markers, including Sox2, CD24, and Prom1/CD133 mRNA levels, were detected in subjects from the TCGA-HNSC dataset." (PMID 38068962, 2023).
cancer (continued). "One cancer stem cell marker SOX2 was up-regulated in HOS-R/DOXO compared to its parental line (log2 FoldChange 1.89, adjusted p value 6,45×10-04), while none of the cancer stem cell markers (SOX2, OCT4, SSEA4, NANOG and ABCG2) were modified in MTX-resistant lines." (PMID 31319571, 2019).
infection (87 papers, 2008 to 2025). The state of being infected such as from the introduction of a foreign agent such as serum, vaccine, antigenic substance or organism. "Examining the earliest timepoint at which we saw growth defects, 7 days post-infection, we stained organoid sections with antibodies against the transcription factor SOX2 and mitogen-associated protein 2 (MAP2), to image NPCs and neurons, respectively." (PMID 40985448, 2025). "Their analysis concluded that the SOX2 gene is also associated with immune response suppression, resulting in higher infection of GSCs by ZIKV." (PMID 39347716, 2024). "We used Rb-NSCs isolated from the Oct4-EGFP transgenic fetuses to tentatively generate Rb-iPSCs through the infection of lentiviral vectors that encode four human transcription factors (Oct4, Sox2, Klf4 and c-Myc)." (PMID 25360692, 2014). "The moderate induction of the typical EpiSC marker T achieved by ablating Sox2 in ESCs prompted us to examine the temporal expression of a panel of genes characteristic of epiblast lineages along with a number of TE- and pluripotency-associated markers in Sox2F/F ESCs following lenti-Cre infection." (PMID 40216251, 2025). "We observed a pronounced reduction in the number of tumorspheres in the Ad-VP3 group, and a time-dependent decrease in the expression of the stemness markers ALDH1A1, KLF4, and Sox2 at 48 and 72 h post-infection." (PMID 41472305, 2025). "The observed reductions in Sox2+ and Sox11+ cells highlight a marked impact of maternal infection on early and intermediate stages of neurogenesis in the hippocampus." (PMID 41567998, 2025). "Immunostaining showed Zika virus penetrating the midbrain, with some viral protein colocalizing with neural stem cells (marked by SOX2) by E15.5, six days after infection (Fig. 3gZ1/Z2)." (PMID 40321761, 2025). "Sox2 was completely removed 48h after infection by lenti-Cre virus, as evident from Western blot analysis." (PMID 40216251, 2025). "In the current study, western immunoblotting of MSCs infected with C. trachomatis L2 demonstrated a significant decrease in total cellular stemness protein markers (Oct4, Nanog, and Sox2) to nearly undetectable levels at 48 h post-infection (h.p.i)." (PMID 39467689, 2024). "The infection studies with brain organoids confirmed the preferential targeting of SOX2+ neural progenitors, which are enriched in the ventricular zone (VZ) and subventricular zone (SVZ) in brain organoids." (PMID 39057782, 2024). "Using bulk infection, we generated a heterogeneous population of SOX2 knockout (KO) fibroblasts that also express the Tet-On system transactivator, M2rtTA." (PMID 37291192, 2023). "Staining of the ZIKVE and neural progenitor cell marker SOX2 showed that these proteins were expressed in brain organoids 14 days after infection." (PMID 35368019, 2022). "Reprogramming was performed using a stoichiometric ratio-based infection of equivalent amounts of retroviruses encoding a POU5 protein (mOct4, X91 or X25) and the three factors KLF4, SOX2, and c-MYC." (PMID 36130934, 2022). "For instance, infection of human induced pluripotent stem cells with IAV diminishes the protein production of SOX2." (PMID 33419104, 2021). "Aiming to investigate the ZIKVBR oncolytic selective infection in vitro, we developed early-stage (26 days) human cerebral organoids with high amounts of SOX2 positive cells." (PMID 34696533, 2021). "A majority of Sox2+ cells remaining 1 week after rAAV infection are GFP positive, indicating that these cells survive despite the vast majority being infected by rAAV (75.6 ± 11.5%)." (PMID 34259630, 2021). "“Surface-TBR1” profile analysis showed decreased width of SOX2+ cell distribution after infection, consistent with VZ thinning (red arrow)." (PMID 33293587, 2020). "Infection phenotype reduced organoid size, ventricle growth, and the expansion of SOX2 and TBR1 cells." (PMID 33293587, 2020).
infection (continued). "Consistently, the data showed that mRNA levels of Oct4 and SOX-2 in NCI-N87 cells were suppressed after infection with lentiviruses expressing small interfering RNAs (siRNAs) against HMGCS1." (PMID 32349352, 2020). "Two days after infection, utricle explants were fixed and stained with antibodies for Myo7a and Sox2." (PMID 31033441, 2019). "We transfected urine cells with SeV encoding OCT3/4, SOX2, KLF4, and c-MYC and found that human embryonic stem cell-like colonies first appeared 5 to 8 days after infection." (PMID 31412925, 2019). "All iPSCs were generated through the infection of fibroblasts with retroviruses encoding OCT4, SOX2, KLF4 and C-MYC, displaying typical features of human pluripotent stem cells." (PMID 27926491, 2017). "In order to elucidate the antitumor effect of the ATF for SOX2, we analyzed cell viability and colony formation of lung SCC cells after Ad-ATF/SOX2 infection." (PMID 29262545, 2017). "Following infection, the transduced cells were selected for puromycin resistance for 24 hours, subcultured into 24-well plates, and probed for Nrf2, Sox2, BMI-1 and Cyclin E by immunocytochemistry." (PMID 23937621, 2013). "We generated these partial iPSCs by infection of MEFs with retroviruses carrying either Oct3/4, Sox2, Klf4, or rtTA genes together with a virus carrying both c-Myc and DsRed cDNAs." (PMID 24386274, 2013). "Our cell proliferation and cell cycle analyses indicated that Sox2 infection into HCT116 cells suppressed proliferation by inducing accumulation of cells in G0/G1 and sub-G1 and reduction of S cell cycle phases compared with mock-infected cells." (PMID 23451179, 2013). "Lentiviral vectors encoding human OCT4, SOX2, KLF4 and c-MYC, at an approximate multiplicity of infection of 5 each, transduced early passage human keratinocytes (HK cells) derived from 56 to 78 year-old individuals with or without T2D." (PMID 22308265, 2012). "At 14 days, pretreatment of MEF with exogenous Klf4 + 100 nM pTAT-mcMyc before Oct4/Sox2 infection at day 0, significantly repressed Thy1 than cells infected with Oct4/Sox2 alone." (PMID 22619682, 2012). "The vulnerability of Sox2 expression to maternal immune activation may be mediated by inflammatory cytokines released in response to infection." (PMID 41567998, 2025). "The Zika viruses are known to target GSCs via SOX2-integrin-mediated infection." (PMID 40342640, 2024). "ACE2 is also expressed in the basal olfactory progenitor cells, and the low number of SOX2-positive cells on day 3 post infection suggests that SARS-CoV-2 infection may have directly impaired the olfactory progenitor cells." (PMID 36339331, 2022). "As shown, IFNβ treatment reduced infection of SOX2+ progenitors." (PMID 36174572, 2022). "Then, 2TS22C ESCs, in which Sox2 protein expression was completely depleted within 2 days after the addition of Dox37, were infected with retroviruses and treated with Dox at 24 h after infection." (PMID 34819616, 2021). "After JEV (SA14) infection, a group of SOX2+ hNPCs are JN1+ (JEV NS1 glycoprotein)." (PMID 29915260, 2018). "All cells, including the IE-positive cells, remained immunoreactive to SOX2, suggesting that infection did not cause detectable changes in the stem cell status of NSCs." (PMID 27078877, 2016). "Finally, incubation of NPC with the pan-caspase inhibitor Z-VAD-FMK prevented the reduction of the population of Sox2+ NPC induced by ZIKV 48 h after infection." (PMID 28008958, 2016). "To determine if PI3K signaling is necessary for the squamous response to SOX2, we treated proliferating basal cell cultures on plastic with pan-class I/II/III and class I-specific PI3K inhibitors LY294002 and BKM120, respectively, concurrently with Lenti-SOX2 infection." (PMID 27880766, 2016). "Interestingly, preinfection with Klf4 (thus prerepressing Thy1), with subsequent Oct4/Sox2 infection, was equally effective at repressing Thy1 at 14 days than infecting cells concurrently with OSK (compare blue and orange lines)." (PMID 22619682, 2012).